NFATC3 (nuclear factor of activated T cells 3)
Diseases named in the same sentence as NFATC3 in open-access papers (continued):
Sharing a sentence is not in itself a finding about the gene and the disease.
glioma (4 papers, 2019 to 2025). A benign or malignant brain and spinal cord tumor that arises from glial cells (astrocytes, oligodendrocytes, ependymal cells). "Furthermore, upregulation of NFATC3 partially recovered the enhanced cisplatin sensitivity of glioma cells caused by circ_0055412 depletion." (PMID 35332692, 2022). "Both quantifications of NFAT expression by qPCR and Western blotting showed that NFATc3 is the most abundantly expressed member of this family in human glioma cells." (PMID 34443374, 2021). "Knockdown of NFATc3 affected proliferation and migration of glioma cells in vitro and orthotropic tumor growth in mice." (PMID 34443374, 2021). "The cell-penetrating peptides Sim-2 or 11R linked to VIVIT did not improve its action making it unsuitable for evaluating NFAT dependent events in glioma cells with high expression of NFATc3." (PMID 34443374, 2021). "All glioma cells showed high levels of NFATc3, while NFATc1 and NFATc2 expression levels were variable among the cells." (PMID 34443374, 2021). "In summary, our data suggest that NFATc3 is highly expressed in human glioma and silencing of this member is critical for RCAN1-4 expression in U251." (PMID 31249342, 2019). "Although we found that NFATc3 is the major member expressed in glioma cells we wanted to evaluate if NFATc1 has a role for the expression of these cytokines." (PMID 31249342, 2019). "Our results support a specific role for NFATc3 in the positive COX-2 regulation in U251 glioma cells, with clear therapeutic implication for the glioma growth." (PMID 31249342, 2019). "Here we show that NFATc3 is required for the normal proliferation and migration capacity of the U251 glioma cells, and for tumour establishment in xenografts." (PMID 31249342, 2019). "Next, considering that the cells inoculated in the mouse model appeared to have remained in the same site of injection, we decided to investigate the effect of NFATc3 knockdown on the migration capacity of U251 glioma cells in vitro." (PMID 31249342, 2019). "Our results indicate that NFATc3 is the most expressed NFATc member in U251 and other hGB cell lines and in an array of human glioma samples according to published databases." (PMID 31249342, 2019). "The CXCL10/CXCR-3 axis has been shown to be expressed in glioma cells, and NFATc3 dependent regulation of CXCR3 is on line with the role of this receptor in migration and site specific dissemination in many cancerous cells." (PMID 31249342, 2019). "We showed that NFATc3 has a positive role in tumour growth, since NFATc3 knock-down inhibits both proliferation and migration of U251 glioma cells as a model." (PMID 31249342, 2019). "Our results suggest that NFATc3 alone is able to modulate a cytokine network required for the normal growth of glioma." (PMID 31249342, 2019). "TCGA data show that all members are overexpressed in grade IV glioma samples, and our data suggest a role of NFATc3 in earlier phases, during the establishment of the tumour." (PMID 31249342, 2019). "After 4 hours, the number of KD-c3 cells migrating through the membrane of the transwell chamber was reduced when compared with KD-Sc cells, indicating the strong participation of NFATc3 in the glioma cells migration." (PMID 31249342, 2019). "Unlike in the immune cells with dominant expression of NFATc2, NFATc3 in glioma cells could still interact with calcineurin through an alternative binding site and remain activated despite blocking of the PxIxIT docking site by 11R-VIVIT." (PMID 34443374, 2021). "Western blot analysis confirmed the abundance of NFATc3 in tested glioma cells." (PMID 34443374, 2021). "This could contribute to different effects of 11R-VIVIT in glioma cells, which express mainly NFATc3." (PMID 34443374, 2021). "Tools limiting NFATc3 might be considered useful to explore future therapeutic approaches against glioma." (PMID 31249342, 2019). "Our data open the possibility of NFATc3 as a target for the treatment of glioma." (PMID 31249342, 2019).
glioma (continued). "Therefore, we questioned the specific contribution of NFATc3 to this process by analysing the effect of NFATc3 silencing in the U251 glioma growth in vitro." (PMID 31249342, 2019). "In addition, we suggest here that NFATc3 is a key positive regulator of RCAN1-4, COX-2; TNF-α; CXCR-3, GM-CSF and IL-2, known to be implicated in glioma growth." (PMID 31249342, 2019). "In addition NFATc3 knock-down affects both the proliferation and migration capacities of glioma cells in vitro." (PMID 31249342, 2019). "In conclusion, our study elucidates the regulatory mechanism that circ_0055412 regulated EIF4A3/CAPG axis and miR‐330‐3p/NFATC3/Wnt/β‐catenin pathway to promote cisplatin resistance of glioma cells, which might provide the theoretical and practical basis for glioma therapy." (PMID 35332692, 2022). "Therefore, it is quite plausible that the inhibition of the abundant NFATc3 in U251 might be able to partially compromise the IL-8 transcription in glioma cells." (PMID 31249342, 2019). "Combining the results obtained by silencing or over-expressing NFATc3, this study indicates that this member is involved in RCAN1-4, COX-2, TNF-α, IL-2, GM-CSF and CXCR-3 gene regulation in U251 glioma cells." (PMID 31249342, 2019). "On the other hand, circ_0055412 sequestered miR‐330‐3p and regulated NFATC3 expression to promote the transcription of CTNNB1, which enhanced β‐catenin and activated Wnt/β‐catenin pathway, thereby improving the cisplatin resistance of glioma cells." (PMID 35332692, 2022). "By using TaqMan probes with similar efficiency, NFATc3 dCt negative values imply that this member is the most abundant in glioma samples." (PMID 31249342, 2019).
myocardial infarction (4 papers, 2014 to 2022). Gross necrosis of the myocardium, as a result of interruption of the blood supply to the area, as in coronary thrombosis. "However, in adult mouse ventricular myocytes, activation of CaN/NFATc3 after myocardial infarction or chronic β-adrenergic stimulation reduced Kv4.2 expression." (PMID 27307045, 2016). "These suggest that BMSCs may reverse potassium channels remodelling via blocking Ca2+/calcineurin/NFATc3 signalling pathway after myocardial infarction." (PMID 24780005, 2014). "These suggest that BMSCs transplantation attenuates myocardial infarction-induced potassium channels remodelling possibly through blocking calcineurin/NFATc3 signalling pathway, which partially contributes to the protective effects of BMSCs on post-infarcted arrhythmias." (PMID 24780005, 2014).
pulmonary hypertension (4 papers, 2017 to 2023). Increased pressure within the pulmonary circulation due to lung or heart disorder. "The activation of NFATC3 and NFATC4 by hypoxia is associated with pulmonary hypertension due to the thickening and stiffening of pulmonary arteries." (PMID 36077479, 2022). "Some studies have demonstrated that NFATc3 was related to pulmonary hypertension induced by CIH in mice, however, the mechanism by which RhoA/ROCK/NFATc3 mediates CIH-induced endothelial dysfunction has not been fully clarified." (PMID 29641598, 2018). "Consistent a possible role of NFAT in the pathogenesis of the inflammation present in COPD, we have previously demonstrated that NFATc3 is required for CH-induced pulmonary hypertension in mice." (PMID 28125639, 2017).
schizophrenia (4 papers, 2018 to 2023). A major psychotic disorder characterized by abnormalities in the perception or expression of reality. "A genome-wide association study found that six immune candidates, namely, DPP4, HSPD1, EGR1, CLU, ESAM, and NFATC3, were associated with schizophrenia." (PMID 35757702, 2022). "Among the FG loci with sex-homogeneous effects, variants at the MANBA/UBE2D3, NFATC3, and IGF1R provided insights into pathways involved in glucose homeostasis and relationships with other complex phenotypes, including neurodegeneration, schizophrenia, and cancer." (PMID 33402679, 2021).
atrial fibrillation (3 papers, 2013 to 2019). A disorder characterized by an electrocardiographic finding of a supraventricular arrhythmia characterized by the replacement of consistent P waves by rapid oscillations or fibrillatory waves that vary in size, shape and timing and are accompanied by an irregular ventricular response. "The isoforms NFATc3 and NFATc4 are active during pathophysiological conditions that affect the cardiovascular system, including atrial fibrillation and hypertrophy." (PMID 23533546, 2013).
Hepatic steatosis (3 papers, 2019 to 2023). Steatosis is a term used to denote lipid accumulation within hepatocytes. "Nfatc3-/- mice showed adipose tissue macrophage polarization toward alternative activation, which significantly reduced hepatic steatosis and inflammation in HFD mice, indicating the potential role of NFATc3 in promoting adipose tissue inflammation." (PMID 37153549, 2023). "Nuclear factor of activated T cells 3 (NFATc3)-knockout markedly attenuated HFD-triggered insulin resistance, liver steatosis, and importantly neuroinflammation and apoptosis, which was attributed to the reduced activation of p38s/JNKs signaling pathways." (PMID 32872540, 2020).
Hypertension (3 papers, 2015 to 2025). The presence of chronic increased pressure in the systemic arterial system. "Persisting [Ca2+]i may be responsible for elevated blood pressure, activating the pro-hypertensive calcineurin/NFATc3 signaling cascade during AngII-induced hypertension." (PMID 40698138, 2025). "Notably, compared to that in controls, NFATc3 expression was increased in patients with TAAD without hypertension." (PMID 40698138, 2025). "In our present study, DF treatment and exercise significantly reduced the expression of fibrotic protein markers such as uPA, CTGF, COL1A1, and COL3A1, as well as hypertrophy markers such as NFATC3, GATA4, BNP, and ANP, which indicates that it could attenuate hypertension-mediated myocardial injury." (PMID 35890118, 2022).
myeloma (3 papers, 2016 to 2022). "Evidence has shown that TRPV2 mediates the secretion of RANKL via the Ca2+-calcineurin-nuclear factor of activated T cells 3 (NFATc3) signaling pathway in multiple myeloma (MM) cells, and RANKL levels are demonstrated in a Ca2+ dose-dependent way." (PMID 36071984, 2022).
Obesity (3 papers, 2023 to 2025). Accumulation of substantial excess body fat. "NFATC3 has established roles in macrophage polarization and immune cell activity, processes critical to obesity-induced inflammation." (PMID 40118008, 2025). "NFATc3 plays a key role in adipose tissue inflammation and insulin resistance in obesity by activating pro-inflammatory genes." (PMID 39596317, 2024).
T cell lymphomas (3 papers, 2012 to 2021). "In T-cell lymphomas, NFATc3 has been identified as a tumor suppressor." (PMID 34917508, 2021).
chronic obstructive pulmonary disease (2 papers, 2017 to 2024). A chronic and progressive lung disorder characterized by the loss of elasticity of the bronchial tree and the air sacs, destruction of the air sacs wall, thickening of the bronchial wall, and mucous accumulation in the bronchial tree. "This crucial capability facilitates the probing of condition-associated genes, exemplified by the discernment of noteworthy candidates such as NFATC3, associated with chronic obstructive pulmonary disease, and MAGEA6, linked to pancreatic ductal adenocarcinoma." (PMID 38493095, 2024).
endothelial dysfunction (2 papers, 2018 to 2021). In vascular diseases, endothelial dysfunction is a systemic pathological state of the endothelium (the inner lining of blood vessels) and can be broadly defined as an imbalance between vasodilating and vasoconstricting substances produced by (or acting on) the endothelium. "In conclusion, this study demonstrates that CIH-induced endothelial dysfunction in OSA is mediated by eNOS/NO reduction through RhoA/ROCK/NFATc3 pathway activation." (PMID 29641598, 2018). "The results suggested that the pathway of RhoA/ROCK/NFATc3 contributed to endothelial dysfunction by CIH." (PMID 29641598, 2018). "In the study, we imitated OSA using a rat model of CIH to investigate the role of ROCK, and detected whether CIH might affect RhoA/ROCK/NFATc3 mediated endothelial dysfunction in aortas." (PMID 29641598, 2018). "NFATc3 is considered a downstream substrate of ROCK and may be involved in CIH-induced endothelial dysfunction." (PMID 29641598, 2018).
fibrosis (2 papers, 2023 to 2024). the formation of excess fibrous connective tissue in an organ or tissue in a reparative or reactive process. "Consistent with fibrosis scores, expression of the other fibrotic markers, α-smooth muscle cell actin (α-SMA) and fibronectin decreased significantly in NFATc3+/- fibrosis mice." (PMID 37523510, 2023). "The expression levels of CCL2 and CXCL2 were significantly lower in the lungs of BLM-induced NFATc3+/- fibrosis mice compared to those of NFATc3+/+ mice." (PMID 37523510, 2023).
glaucoma (2 papers, 2023 to 2024). Increased pressure in the eyeball due to obstruction of the outflow of aqueous humor. "Moreover, we found that cyclosporin A blocked NFATc3 nuclear translocation, which reduced the ECM fibrosis gene expression in glaucoma LC fibroblasts." (PMID 36674805, 2023).
hepatocellular carcinoma (2 papers, 2021 to 2024). A malignant tumor that arises from hepatocytes. "In hepatocellular carcinoma, NFATc3 is frequently deleted or downregulated, which is associated with a poor prognosis among hepatocellular carcinoma patients." (PMID 34917508, 2021). "For cancer, there are various types of cancer associated with the protein, such as the effect of NFATc3 on hepatitis B virus (HBV) replication and hepatocarcinogenesis, making it a promising target for hepatitis B-induced hepatocellular carcinoma." (PMID 39822413, 2024). "NFATc3 binds to the promoter regions of IFNL1 and IFNB1 to activate their transcription in a synergistic manner with the RIG-I pathway, which can inhibit hepatitis B virus replication and hepatocellular carcinoma tumorigenesis." (PMID 39822413, 2024).
intestinal tumors (2 papers, 2020 to 2024). "Butyrate suppresses intestinal tumour cell proliferation by inhibiting calcineurin‐mediated activation of the nuclear factor of activated T cells 3 (NFATc3) transcription factor." (PMID 39568157, 2024).
liposarcoma (2 papers, 2021 to 2025). A usually painless malignant tumor that arises from adipose tissue. "Stimulating the MAPK pathway is known to increase the tumour staging and is associated with poor prognosis in liposarcoma such as dedifferentiated liposarcoma while activating NFATC3 was previously found to promote the growth and migration of tumours such as glioma." (PMID 39736850, 2025). "Nevertheless, this discovery contradicts the previous observation that LINC00423 plays a tumour-repressing role by controlling the NFATC3 activity liposarcoma." (PMID 39736850, 2025). "For instance, the overexpression of linc00423, a downregulated lncRNA in liposarcoma patients, has been found to inhibit liposarcoma cell proliferation and colony formation by suppressing the MAPK signaling pathway via direct binding with NFATC3 in vivo and in vitro." (PMID 34733885, 2021).
lung injury (2 papers, 2021 to 2023). "In acute lung injury, TRP vanilloid 4 (TRPV4)-dependent Ca2+ influx contributes to LPS-induced macrophage activation, a process associated with the calcineurin-NFATc3 pathway." (PMID 34507301, 2021). "For example, NFATc3 transcriptionally regulates the expression of tumor necrosis factor alpha (TNF-α), promoting the progression of LPS-induced acute lung injury." (PMID 36825443, 2023).
neuroblastoma (2 papers, 2019 to 2022). Neuroblastoma (NB) is the most common solid, extracranial childhood tumor. "A recent research showed that calcineurin-NFATc3 inhibition by calcineurin inhibitor treatment restrained cell proliferation and increased apoptosis of neuroblastoma cells." (PMID 31519770, 2019).
oral squamous cell carcinoma (2 papers, 2022). "NFATC3 has been demonstrated to play the oncogenic role in oral squamous cell carcinoma." (PMID 35332692, 2022).
oropharyngeal squamous cell carcinoma (2 papers, 2019 to 2021). "We here report that NFATc3 is the dominant isoform of NFAT in human oral epithelial cells, and its expression was increased in a stepwise manner during the progression of oral/oropharyngeal squamous cell carcinoma (OSCC)." (PMID 31040921, 2019).
renal fibrosis (2 papers, 2022 to 2025). A final common manifestation of a wide variety of chronic kidney diseases characterized by glomerulosclerosis and tubulointerstitial fibrosis. "Previous studies have shown that podocyte injury promotes renal fibrosis by inducing abnormal ECM protein expression and accumulation, with NFATc3 activation identified as a critical regulatory factor in this process." (PMID 40520074, 2025). "Masson's staining revealed extensive renal fibrosis, which was further aggravated in the LRRC55‐overexpression group, whereas fibrosis was significantly alleviated in the NFATc3‐knockdown group." (PMID 40520074, 2025).